LEPR (leptin receptor)
Diseases named in the same sentence as LEPR in open-access papers (continued):
Sharing a sentence is not in itself a finding about the gene and the disease.
osteoporosis (13 papers, 2010 to 2025). A condition of reduced bone mass, with decreased cortical thickness and a decrease in the number and size of the trabeculae of cancellous bone (but normal chemical composition), resulting in increased fracture incidence. "Pulsed electromagnetic fields (PEMFs) attenuated the senescence of LepR+ BMSCs to prevent bone loss in glucocorticoid-induced osteoporosis." (PMID 36233230, 2022). "The aim of this study was to evaluate bony statues at microarchitectural level to determine whether leptin receptor-deficient mice model was a potentially valid animal model for type 2 DM-associated secondary osteoporosis." (PMID 27283954, 2016). "miR155 has been shown to be upregulated in osteoporosis, in which it targets the leptin receptor (LEPR)." (PMID 39452495, 2024). "Overall, Prx1+, Osx+ BMSCs exhibited lower osteogenic capacity in mice with osteoporosis, and active Thy+/6c3− and LepR+ BMSCs by Jun addition or PEMFs can attenuate osteoporosis in mice." (PMID 36233230, 2022). "Another variant is LEPR (rs1137100 A/G), with the AA homozygote being associated with osteoporosis progression in Chinese Mulao populations but not in Danish populations." (PMID 41303600, 2025). "For example, since the LepR displayed on MSCs in the bone marrow inhibits osteogenesis and promotes adipogenesis, it can be hypothesized that the use of LepR antagonists could be beneficial for osteoporosis therapies." (PMID 38727260, 2024). "The leptin-receptor mice is not a proper model for secondary osteoporosis associated with T2DM." (PMID 27283954, 2016). "Leptin receptor knock-out type 2 DM mice did not exhibit phenotype, on a bone microarchitectural level, typical of osteoporosis." (PMID 27283954, 2016).
atherosclerosis (12 papers, 2012 to 2023). A disease characterized by the build-up of fatty material and calcium deposition in the arterial wall resulting in partial or complete occlusion of the arterial lumen. "The rs1137100 SNP in the LEPR gene was independently associated with early atherosclerosis and some risk factors of IR." (PMID 36984867, 2023). "Leptin has previously been implicated in the development of atherosclerosis due to the presence of the leptin receptor in atherosclerotic lesions." (PMID 36853380, 2023). "They revealed that LEPR 223 GG genotype carriers may be at a higher risk of the development of early atherosclerosis in acromegaly than other genotype carriers." (PMID 37446150, 2023). "We have identified seven genes (CHI3L1, CD36, LEPR, RETN, IL-18, RBP-4, and RARRES2) that may be associated with IR and atherosclerosis as having possible evidence based on the disease pathogenesis of ED and inflammation." (PMID 36984867, 2023). "Changes in the expression of leptin and LEPR due to genetic and environmental factors may lead to dysfunction of the leptin system, disturbances in energy balance, weight gain, and risk for developing T2DM or atherosclerosis." (PMID 36984867, 2023). "This review focuses on the link between IR, T2DM, atherosclerosis, CAD, and the potential genetic markers CHI3L1, CD36, LEPR, RETN, IL-18, RBP-4, and RARRES2 genes." (PMID 36984867, 2023). "This review identified CHI3L1, CD36, LEPR, RETN, IL-18, RBP-4, and RARRES2 genes as the potential genetic markers of IR and atherosclerosis in T2DM patients with CAD." (PMID 36984867, 2023). "In addition, we evaluated the potential relationship between HNF1A rs1183910, LEPR rs4420065, GCKR rs1260326, NLRP3 rs12239046, IL1F10 rs6734238, PPP1R3B rs9987289, ASCL1 rs10745954, HNF4A rs1800961 and SALL1 rs10521222 polymorphisms and CV events or subclinical atherosclerosis in RA patients." (PMID 27534721, 2016).
colon carcinoma (12 papers, 2013 to 2024). "Slettery and colleagues first explored the relationship of LEPR rs6588147 with the occurrence of colon cancer and indicated that A allele of rs6588147 had a tendency to reduce the occurrence of colon cancer in Caucasians." (PMID 38659416, 2024). "Significant decrease of tumor cell proliferation was observed in leptin-deficient tumors, and colon tumor growth was dramatically inhibited in leptin-deficient and leptin-receptor-deficient mice." (PMID 23593308, 2013). "Haplotype analysis indicated that the haplotype G-C-T in block 2 and haplotype A-A-G in block 3 on LEPR were associated with prolonged OS and DFS among patients with CRC overall and patients with colon cancer, as compared with the most common haplotype." (PMID 37282602, 2023). "Oral administration of probiotics significantly reduced leptin receptor gene expression in mice with colon cancer." (PMID 37684563, 2023). "Through binding to the receptor LEPR, leptin/LEPR signaling has been shown to be related to the progression of a large number of cancers, such as pancreas and colon cancers." (PMID 35115495, 2022). "We have previously reported that colon cells possess leptin receptor and that leptin promotes colon cancer initiation and progression, in vitro, in addition to cell proliferation and tumor growth." (PMID 24073224, 2013). "The haplotype A-A-G situated in LD block 3 of LEPR (rs7602-rs970467-rs9436748) was significantly associated with increased OS (HR, 0.49; 95% CI, 0.29–0.83) and DFS (HR, 0.58; 95% CI, 0.34–0.99) for patients with colon cancer." (PMID 37282602, 2023). "Many studies have also demonstrated over-expression of LEPR in colon cancer." (PMID 31592340, 2019). "We have shown in our previous publication that by using an antagonist to the leptin receptor we could detect a significant protection against OCR reduction induced by CM collected from obese subjects in HCT116 human colon cancer cells." (PMID 26472027, 2015). "The leptin receptor was expressed in human colon cancer cell lines and human colonic tissue." (PMID 23593308, 2013). "Haplotype analyses indicated that the LEPR block 2 haplotype G-C-T, defined by rs7534511, rs9436301, and rs1887285, and the block 3 haplotype A-A-G, defined by rs7602, rs970467, and rs9436748, were associated with prolonged OS and DFS among patients with CRC and colon cancer." (PMID 37282602, 2023). "In the following, we assessed the effects of these probiotics on the gene expression of vitamin D receptor (VDR) and the leptin receptor (LPR) and the serum biochemical parameters on mice colon cancer." (PMID 31231490, 2019).
pancreatic cancer (12 papers, 2015 to 2022). "Leptin induces cell migration, invasion, and metastasis in an orthotopic model of pancreatic cancer, and the simultaneous increase in the expression of leptin receptor and MMP13 also shows a positive association with the TNM stage." (PMID 33804101, 2021). "In vitro studies demonstrated growth and metastasis of a murine pancreatic cancer cell line was shown to be increased in genetically obese mice caused by loss of leptin or loss of the long isoform of the leptin receptor." (PMID 25919692, 2015). "Similarly, using MPE, Babic and colleagues showed that higher levels of plasma leptin were associated with increased risk of pancreatic cancer in men, whereas in women a single nucleotide variant at the leptin receptor gene (rs10493380) was associated with pancreatic cancer risk." (PMID 30249004, 2018). "Similarly, in vitro treatment of recombinant leptin to pancreatic cancer cells caused a significant increase in p-Akt in Panc-02 and Panc-1 pancreatic cancer cells, but MiaPaCa-2 cells did not activate p-Akt in response to leptin regarded to the short and long forms of the leptin receptor in cells." (PMID 37529006, 2022). "LEPR overexpression in pancreatic tumor tissue stimulates proliferation, migration, and angiogenesis, while reducing apoptosis rates." (PMID 33670492, 2021). "Reduction of leptin receptor by shRNA knockdown was observed to partially abrogate tumor growth in obese mice of orthotopic murine pancreatic cancer model." (PMID 33799880, 2021). "In pancreatic cancer, leptin induced cancer cell migration/invasion and metastasis in orthotopic model, and the simultaneously increased leptin receptor and MMP13 production displayed the positive correlation with patient's TNM stages." (PMID 29682217, 2018). "The role of leptin and leptin receptor signaling in pancreatic cancer development and progression remains ill defined." (PMID 25919692, 2015). "Human and murine pancreatic cancer cell lines were found to express the short as well as the long form of the leptin receptor and functionally responded to leptin induced activation through an increased phosphorylation of AKT473." (PMID 25919692, 2015). "In order to determine the contribution of the leptin receptor to pancreatic cancer growth in obese mice, we knocked down the expression of the leptin receptor using lentiviral shRNAmir based techniques in the murine Panc02 cell line." (PMID 25919692, 2015). "We demonstrated that the leptin receptor Ob-Rb is present in pancreatic cancer cells, and the activation of Ob-Rb can enhance the invasion of pancreatic cancer via upregulating MMP-13 production." (PMID 25948792, 2015). "The role of leptin receptor in pancreatic cancer was also reported." (PMID 33799880, 2021). "Both the short isoform (LR-short) and the long form (LR-Long) were present in pancreatic cancer cell lines, yet the long form in human lines was only weakly detected using the K-20 antibody Presence of the long leptin receptor isoform was additionally verified using the H-300 antibody." (PMID 25919692, 2015). "A recent study reported that the leptin receptor was detected in pancreatic cancer cells, and hypoxia inducible factor (HIF)-1α could directly regulate its expression." (PMID 25948792, 2015). "In addition, simultaneously high leptin receptor and MMP13 production exhibited a positive correlation with TNM status in pancreatic cancer patients." (PMID 33799880, 2021). "The pancreatic cancer cells PANC1 and AsPC1 express Ob-Rb (a leptin receptor)." (PMID 33670492, 2021). "Leptin can specifically bind to the leptin receptor (ObR) expressed in pancreatic cancer and promote the migration and invasion of pancreatic cancer cells but does not affect the proliferation ability of pancreatic cancer cells." (PMID 34485124, 2021). "Results demonstrate that leptin receptor expression potentiates pancreatic tumor growth independent of tumor cell proliferation." (PMID 25919692, 2015).
prostate carcinoma (11 papers, 2012 to 2026). A carcinoma that arises from epithelial cells of the prostate gland. "In linear regression analysis, the relative risk of prostate cancer was associated only with serum tPSA and leptin receptor mRNA expression (P = .0001)." (PMID 32573960, 2020). "This study revealed that the expression levels of leptin and leptin receptor mRNA are suggested to be the potential biomarkers for risk of prostate cancer." (PMID 32573960, 2020). "Both high levels of leptin in circulation and leptin receptor mutation are associated with prostate cancer risk in human patients; however, the in vivo mechanistic evidence is less conclusive." (PMID 26376613, 2015). "In the prostate cancer group with high risk for metastasis, only the LEPR Gln223Arg, SPP1-66 T>G and FGF2+223 C>T genetic variants, age and PSA persisted." (PMID 22792137, 2012). "In addition, a positive association between LEPR mRNA expression and unfavorable prognosis was found in prostate cancer." (PMID 33799880, 2021). "Leptin receptor mutation is significantly associated with an increased risk of prostate cancer." (PMID 26376613, 2015). "Indeed, meta-analysis of 16 published studies of 6569 cases and 8405 controls for the leptin receptor G2548A mutation showed that it is statistically significantly associated with an increased risk of prostate cancer (OR=1.26, 95% CI=1.05-1.51)." (PMID 26376613, 2015). "A similar positive correlation was also discovered between leptin/leptin receptor overexpression and distant metastasis in a cohort of 176 prostate cancer patients." (PMID 33799880, 2021). "The mRNA level of LepR, AdipoR1 and AdipoR2 is low in normal mouse prostate, but the situation in the prostate cancer is different." (PMID 30013512, 2018). "Leptin receptor antagonists have been investigated in breast and prostate cancers, which mainly are hormone dependent." (PMID 28861689, 2017). "In vitro, it has been shown that human prostate cancers express the leptin receptor and leptin is able to stimulate growth of some human prostate cancer cell lines." (PMID 22690216, 2012). "Prostate cancers express the leptin receptor and leptin staining is significantly increased in malignant prostates and poorly differentiated tumors." (PMID 23009291, 2012). "Leptin receptor mRNA expression might be considered an independent predictor of aggressive prostate cancer; further studies on larger cohort are needed to confirm these findings." (PMID 32573960, 2020). "On the contrary, LEPR rs1137101 (allele contrast: OR 0.843, 95%CI 0.730-0.973) and ADIPOR1 rs2232853 (allele contrast: OR 0.638, 95%CI 0.535-0.760) variants were associated with decreased risk of prostate cancer." (PMID 27768592, 2016). "In conclusion, this meta-analysis found that the LEP 2548AA genotype was associated with a weakly increased risk of cancer, mainly for prostate cancer, while LEPR Q223R was not." (PMID 24146750, 2013). "The SNPs in LEPR Gln223Arg, SPP1-66 T>G, IGF1R+3174 G>A, IGFBP3-202 A>C, FGF2+223 C>T and IL6-597 G>A, plus age and PSA remained independently associated with risk for overall, and for high-grade prostate cancer." (PMID 22792137, 2012). "Conversely, we found an increased risk in LEPR Gln223Arg homozygous A for prostate cancer, whereas others observed no such association." (PMID 22792137, 2012). "Interestingly, we found that both the LEPR Gln223Arg homozygous A and SPP1-66 homozygous G were significantly associated with all outcomes (risks of overall, high-grade, and high metastatic-risk prostate cancers)." (PMID 22792137, 2012). "The expression of leptin receptor (LEPR) in prostate cancer influences the extent of tumour differentiation with no remarkable correlation between leptin levels in tumour tissues and BMI or between circulating plasma leptin levels and BMI." (PMID 26376613, 2015).
prostate carcinoma (continued). "Adipocyte derived leptin promoted the proliferation of androgen-independent human prostate cancer cell lines DU145 and PC-3 rather than androgen-dependent LNCaP-FGC cells, although both cell types expressed functional LepR isoforms." (PMID 30013512, 2018).
asthma (10 papers, 2010 to 2026). "The aim of our study was to investigate the association of the prognostic role of leptin and adiponectin, as well as the leptin receptor gene polymorphism Gln223Arg, in patients with difficult-to-control and severe asthma." (PMID 40361972, 2025). "There are very limited data in the literature on the effect of polymorphisms in the leptin receptor gene in patients with asthma." (PMID 40361972, 2025). "The identified sex-related effect modification of the acetaminophen-asthma association varied across LEPR genotypes, indicating that the sex-specific association was confined to individuals with certain genetic susceptibility." (PMID 30231898, 2018). "We demonstrated that acetaminophen use increased the risk of asthma to a similar magnitude in males and females who carry two copies of the wild-type allele of LEPR SNPs." (PMID 30231898, 2018). "Our previous study performed on LEP and LEPR gene polymorphism showed an association of rs13228377 polymorphism with childhood asthma with AA risk genotype and A risk allele in a cohort of Polish children." (PMID 30203371, 2018). "Associations between acetaminophen use and current asthma stratified by sex and genotypes of leptin receptor (LEPR) gene polymorphisms: results from the Isle of Wight study." (PMID 30231898, 2018). "In contrast, among those carrying at least one copy of the minor allele for LEPR SNPs, the magnitude of the acetaminophen use effect on asthma was highly pronounced among males (rs17415296: aPR = 6.83,), but not among females (rs17415296: aPR = 1.22)." (PMID 30231898, 2018). "Evaluating three-way statistical interactions on a multiplicative scale between sex, acetaminophen use and polymorphisms in leptin (LEP) and leptin receptor (LEPR) genes on the risk of current asthma: results from the Isle of Wight study." (PMID 30231898, 2018). "Taking into account previous reports, we investigated if two LEPR polymorphisms, K109R and Q223R, are associated with asthma risk or serum levels of leptin receptor or leptin." (PMID 30203371, 2018). "After adjusting for multiple testing, the screening process revealed the presence of three-way interactions between four LEPR SNPs, sex, and acetaminophen use on the risk of current asthma." (PMID 30231898, 2018). "First, leptin and leptin receptor are expressed in lung tissue and their expression levels have been shown to be associated with asthma development and severity." (PMID 30231898, 2018). "Whereas, carrying at least one copy of the minor allele of LEPR SNPs lead to a sex-related differential effect of acetaminophen use on asthma risk." (PMID 30231898, 2018). "So far, no study analyzing the role of leptin receptor gene (LEPR) polymorphism on leptin receptor serum level in asthma has been performed." (PMID 30203371, 2018). "In contrast, among individuals homozygous for the common allele of LEPR SNPs, acetaminophen associated with asthma among males and females to a similar magnitude of effect, indicating that acetaminophen effect was modulated by sex and genetic make-up." (PMID 30231898, 2018). "Our findings suggest a role of leptin in enhancing neutrophil survival in asthma disease which are associated with altered levels of leptin receptor." (PMID 23383125, 2013). "Furthermore, we demonstrated for the first time that genotypes of LEPR SNPs modified the observed sex-specific acetaminophen-asthma association." (PMID 30231898, 2018). "Moreover, the proposed mechanism of action linking acetaminophen use and leptin/leptin receptor on asthma risk seems to be further modulated by sex." (PMID 30231898, 2018). "We also aimed to analyze if leptin receptor level or gene polymorphism may influence leptin level and asthma risk." (PMID 30203371, 2018). "Moreover, sex- and genotype-stratified analysis indicated that acetaminophen use was associated with asthma to a similar extent among male and female participants carrying two wild-type alleles of LEPR SNPs." (PMID 30231898, 2018).